MMP9 (matrix metallopeptidase 9)
Diseases named in the same sentence as MMP9 in open-access papers (continued):
Sharing a sentence is not in itself a finding about the gene and the disease.
tumor (continued). "MDSCs also harbour tumor-promoting functions by non-immunological mechanisms, such as the promotion of angiogenesis (via VEGF and angiopoietins production) and matrix remodelling (via MMP9 expression), thus enabling cancer cells to move from the primary tumor to metastatic sites." (PMID 32823961, 2020). "To understand whether exosomes were involved in the regulation of MMP3 protein levels and MMP9 activities in tumor patients, we analyzed MMP3 protein levels and MMP9 activities in lung tumor tissues from obese tumor patients with or without amiloride treatment." (PMID 29137230, 2017). "As expected, the involvement of tumor microenvironment in cancer and in its complications, such as DVT, is emphasized in the correlation between plasma levels of IL-6,TNF-α, IL-1β, VEGF and MMP-9 from cancer patients with and without DVT and those released from monocytes." (PMID 26192925, 2015). "In vitro experimental results showed that although RLX could increase the expression of MMP-9, it did not increase the invasion and metastasis ability of the tumor, suggesting that RLX influenced the tumor microenvironment rather than directly affecting tumor cells." (PMID 38955827, 2024). "However, we also noted that adding EVs from tumor cells, independent of the presence of CD147, increased the levels of released MMP2 and active MMP9 above that of astrocytes receiving no vesicles, suggesting that other elements in EVs may contribute to this process." (PMID 32033611, 2020). "Although bexarotene did not significantly change MMP2 secretion in A549 cells and MMP9 in MDA-MB-231 cells, the decreased amount of other matrix metalloproteinases and elevated level of TIMPs may result in an increased ratio of TIMP to MMP leading to a decrease in tumour cell invasion." (PMID 16495926, 2006). "In addition, MDSCs may harbor tumor-promoting functions that are independent of immune suppression, such as promoting metastasis and angiogenesis through the production of vascular endothelial growth factor (VEGF), fibroblast growth factor β (FGF-β) and matrix metalloproteinase-9 (MMP9)." (PMID 36532078, 2022). "Besides, the result that activation of ERK and PI3K-AKT pathways significantly increased the level of MMP-9 in Chang liver cells suggests that AKT and ERK pathways-dependent MMP-9 expression may also exist in Chang liver cells and not be specific to tumor cells." (PMID 21738655, 2011).
cancer (3,316 papers, 1995 to 2026). A tumor composed of atypical neoplastic, often pleomorphic cells that invade other tissues. "This functional complexity underlies why MMP-9 remains a compelling yet technically challenging therapeutic target in cancer biology." (PMID 41304763, 2025). "Numerous studies have underscored Snail-1’s impact on EMT-associated molecules, including E-cadherin, vimentin, MMP-9, and microRNAs like miR-34a, shaping cancer cells’ invasive, migratory, and metastatic potential." (PMID 40575155, 2025). "Dysregulation of MMP-9 is linked with various disorders, including inflammatory diseases or cancers." (PMID 40869267, 2025). "Elevated levels of MMP-2 and MMP-9 have been implicated in the progression and metastasis of various cancers, including those of the bladder, breast, cervix, colon, and others." (PMID 40563423, 2025). "Located in the 20q12-13 region of the human chromosome, MMP-9 has been implicated in various cancer types." (PMID 41179937, 2025). "Western blot analysis of MMP-2 and MMP-9, proteins associated with cancer invasion and metastasis, aligned with the Transwell results." (PMID 39508798, 2025). "The overexpression and secretion of MMP-2 and MMP-9 is increased in several types of human cancers and is associated with poor prognosis." (PMID 39941886, 2025). "The matrix metalloproteinase family, including MMP1, MMP2, and MMP9, causes cancer cell invasion and migration during cancer progression." (PMID 40093316, 2025). "Plumbagin has been shown to inactivate the main pathways associated with the proliferation of cancer cells, including matrix metalloproteinase-9 (MMP-9), Akt/NF-κB, and vascular endothelial growth factor, thereby preventing cancer progression." (PMID 40410881, 2025). "MMP9, a key regulator of extracellular matrix components, is associated with cancer and inflammation." (PMID 40363725, 2025). "It has been previously reported that NETs and NET-associated functional molecules, such as NE and MMP-9, can induce migration and invasion in certain types of cancer." (PMID 40155451, 2025). "It is interesting that, in our results, increased matrix metalloproteinase 9 (MMP9) expression shows a tendency for better event-free survival, although MMP9 is typically associated with promoting cancer progression, invasion, and metastasis." (PMID 40870889, 2025). "MMP9, a prominent hub on the protein interaction map, promotes cancer cell invasion and angiogenesis and is associated with poor patient prognosis in solid tumors." (PMID 41445746, 2025). "Although previous studies have implicated MMP9 in extracellular matrix remodeling and leukocyte migration during inflammation and cancer progression, its direct immunosuppressive function in T cells has received limited attention." (PMID 41306770, 2025). "MSLN’s function in facilitating cancer invasion has been demonstrated by its association with matrix metallopeptidase 9 (MMP-9) expression at the invasive margins of malignancies." (PMID 40227645, 2025). "In pancreatic cancer, MMP-2, expressed by activated pancreatic stellate cells, is associated with cancer progression in contrast to MMP-9, which seems to coordinate immune cell infiltration." (PMID 40332096, 2025). "All samples demonstrated a 45–65% reduction in the activity of specific MMPs (MMP-9 and proMMP-9) linked to cancer progression." (PMID 40966212, 2025). "Gene polymorphisms in MMP-2 and MMP-9 can influence their function, impacting cancer development and progression." (PMID 39063556, 2024). "Dysregulated MMP-9 activity has been implicated in various pathological conditions, including cancer, chronic inflammatory diseases, and aging-related disorders." (PMID 39061853, 2024). "Mpro is the viral protease from the SarsCov-2 virus, and MMP9 is a ubiquitous cancer-associated protease involved in cancer-mediated tissue remodelling and metastasis, well studied as a cancer-selective biomarker." (PMID 38646011, 2024).
cancer (continued). "The overexpression of MMP9 has been associated with poor prognosis and increased cancer aggressiveness, making it a potential prognostic biomarker in cancer." (PMID 38560573, 2024). "Some authors focused on exploring the diagnostic utility of the serum MMP-2 and MMP-9 levels in OC patients in relation to the clinicopathological features of cancer." (PMID 38673838, 2024). "The MMP-9 gene plays a pivotal role in cancer cells by encoding matrix metalloproteinase-9, an enzyme involved in the breakdown of extracellular matrix components." (PMID 38481883, 2024). "MMP9 is a member of the matrix metalloproteinase family, which is involved in extracellular matrix breakdown and has been linked to the invasiveness of cancers." (PMID 38398089, 2024). "In HNCs, MMPs, especially MMP-9, are associated with the degradation of the extracellular matrix, which allows cancer to spread via blood vessels." (PMID 38275388, 2023). "MMP2 and MMP9 are a family of proteolytic enzymes implicated in the invasion and metastasis of numerous cancers because they degrade extracellular matrix components." (PMID 37239013, 2023). "Among the numerous MMPs identified (over 20 in total), MMP2 and MMP9 have been linked to the aggressive behavior of cancer." (PMID 38002335, 2023). "In recent years, numerous genetic studies on MMP-2 and MMP-9, along with their roles in cancer risk have been published." (PMID 37445754, 2023). "Concomitantly, MMP2 overexpression is associated with a higher risk of cancer metastasis, and MMP9 overexpression correlates to lymph node metastasis." (PMID 37239013, 2023). "NET-associated proteases, neutrophil elastase, and MMP-9 remodel laminin epitopes, activate integrin alpha-3beta-1 signaling, and induce dormant cancer cell proliferation and metastasis." (PMID 37176151, 2023). "NE from NETs is associated with matrix metalloproteinase-9 (MMP-9) for activation of dormant cancer cells." (PMID 37493409, 2023). "MMP-2 and MMP-9 have also been implicated in cancer development and progression through their functions in cell apoptosis, proliferation, and angiogenesis." (PMID 36831550, 2023). "Matrix metalloproteinase (MMP)-9 encourages angiogenesis and promotes the invasion of many cancers and is the first member of the MMP family to be linked to the invasion of PA." (PMID 36831707, 2023). "Previous studies have shown that MMP-9 has markedly expressed in several cancers, including BC tissues and their associated cancer cells." (PMID 37372062, 2023). "Overexpression of MMP2 and MMP9 is associated with metastatic cell activity in many types of cancer." (PMID 37509417, 2023). "The overexpression of MMP-9 is associated with different cancers, such as lung, prostate, gastric, pancreatic, and colon and with other diseases, such as autoimmune and cardiovascular diseases." (PMID 37764188, 2023). "MMP9 is implicated in cancer development and progression through its activities in cell apoptosis, proliferation, and angiogenesis." (PMID 37587140, 2023). "InTable 1, the polymorphisms of the MMP-9 that have been shown to be correlated to oncogenesis in different types of cancer have been summarized." (PMID 37077369, 2023). "Several disorders, namely cardiovascular diseases, neurodegenerative diseases, central nervous system disorders, and various cancers, are linked to MMP-9 dysregulation and overexpression." (PMID 37037467, 2023). "More specifically, the expression of MMP-9 and polymorphisms of its gene have been found to be correlated with the formation and the invasiveness of different types of cancer." (PMID 37077369, 2023). "Combined with these previous reports, we have further confidence that MMP9 in cancer cells is closely associated with ESCC progression." (PMID 37296952, 2023). "A recent meta-analysis evaluated the relationships of variants in MMP-2, MMP-7, and MMP-9 for cancer risk." (PMID 37138857, 2023).
cancer (continued). "Increased expression of MMP-9 has been reported in various cancer patients, and it is associated with their poor disease prognosis." (PMID 38068928, 2023). "Nonetheless, our findings are consistent with previous reports, which indicate that MMP9 expression in cancer cells is associated with aggressive cancer characteristics and participates in cancer cell motility and invasion in vivo." (PMID 37296952, 2023). "MMP9 is an essential enzyme causing degradation of the basement membrane along with the extracellular matrix, regulating migration and metastasis of cancers." (PMID 35418191, 2022). "NETs are decorated with a variety of proteins, among them neutrophil elastase (NE), cathepsin G (CG), and matrix metalloproteinase 9 (MMP-9), all of which have been implicated in cancer progression." (PMID 35267667, 2022). "We believe that the E3Ab antibody decreasing the migration of cancer cells is associated with the protein expression of MMP-9." (PMID 35204811, 2022). "Panel A was made of MMP-9 as a member of matrix metalloproteinases (MMPs) that are implicated in cancer invasion and metastasis and TIMP-1 as a kind of tissue inhibitor of metalloproteinases (TIMPs)." (PMID 35222743, 2022). "Its activation of miR-9 was associated with an inhibition of metalloproteinase MMP-9 involved in the degradation of the extracellular matrix; was associated with the invasive potential of cancer cells; and modulated the NF-kB pathway, thus enhancing apoptosis." (PMID 36143832, 2022). "High levels of MMP7 are associated with shorter survival in cancer patients, while the prognostic role of MMP9 is controversial." (PMID 35928876, 2022). "This assumption was confirmed by the observed reduction in the secretion of proteases associated with cancer invasion and metastasis (MMP-9, uPA), and an increase in the level of tissue inhibitor of metalloproteinase (TIMP)-1 in cells treated with 10 μM CA." (PMID 35158770, 2022). "MMP-2 and MMP-9 proteins are associated with the invasion, proliferation, and metastasis of cancer cells." (PMID 36291760, 2022). "MMP gene variants (e.g., MMP-2, MMP-7, and MMP-9) can affect the biological functions of these enzymes and lead to the occurrence and progression of cancer, which has become a hot topic in recent years, but the corresponding results are still controversial." (PMID 35574300, 2022). "In this study, the NET-associated proteases NE and MMP-9 were found to be responsible for the reactivation of dormant cancer cells." (PMID 35764882, 2022). "MMP9 is implicated with the malignant progression of cancer, including but not limited to invasion, migration, metastasis, and angiogenesis." (PMID 35912155, 2022). "Several aptamer-based probes have been developed using upregulated membrane-bound or membrane-associated proteolytic enzymes, such as MMP-2, MMp-7, and MMP-9, for cancer diagnosis." (PMID 36431072, 2022). "HIF-2α increases the expression of DLL4 at the transcriptional level by binding directly to site 3 of the DLL4 promoter region, which then activates Notch1 signals, causing downstream secretion of MMP-9 for increased cancer cell migration." (PMID 35385679, 2022). "PubMed, Web of Science, and Medline were systemically searched, and data were extracted from all eligible studies so as to investigate the susceptibility of MMP-2, MMP-7, and MMP-9 to different types of cancers." (PMID 35574300, 2022). "In this context, here, the meta-analysis was conducted for assessing the relations of variants in MMP-2, MMP-7, and MMP-9 with the risk of various cancers." (PMID 35574300, 2022). "Neutrophils treated with cancer-associated a2V showed prolonged survival and elevated pro-angiogenic activity, with elevated expression of MMP-9 and VEGF." (PMID 35158807, 2022).
cancer (continued). "Among the effects of these transcription factors, increased expression of proteases (e.g., MMP-2 and MMP-9) are what cause cancer cells to undergo EMT for promoting cellular detachment and invasiveness." (PMID 35586209, 2022). "Upregulation of MMP-9 is often associated with increased cancer cell migration, invasion, and metastasis." (PMID 36312981, 2022). "In vivo studies using Mmp9−/− mice have demonstrated that MMP9 deficiency is associated with various abnormalities in processes that are relevant for cancer development, such as inflammation, wound healing, and vascular wall remodeling." (PMID 35406619, 2022). "Meta-analyses were conducted for assessing the relations among variants in MMP-2, MMP-7, and MMP-9 and cancer risk." (PMID 35574300, 2022). "Although numerous studies have reported associations between MMP-2, MMP-7, and MMP-9 variants and cancer risk, these results are highly controversial." (PMID 35574300, 2022). "Considering that, this study has the largest scale and is an integrative study that evaluates the relations of MMP-2, MMP-7, and MMP-9 variants with cancer susceptibility." (PMID 35574300, 2022). "Collectively, our results suggested that LDL treatment promotes the cellular invasion capacity of both parental and variant B cells, whereas Cry exerts the opposite effect on this key cancer hallmark by inhibiting MMP-9." (PMID 36552834, 2022). "MMP-9 has been linked to cancer pathophysiology as it plays an important role in ECM remodeling and membrane protein cleavage." (PMID 35463960, 2022). "MMP-9 has been implicated in a number of diseases, including cardiovascular diseases, inflammatory disorders, and cancers." (PMID 36289761, 2022). "Conclusions and implications: Overall, we demonstrated that FQs inhibit cancer cell migration and invasion by downregulating MMP-9 expression and revealed the cellular mechanisms underlying their potential value in cancer treatment." (PMID 34769032, 2021). "Genetic and pharmacological loss‐of‐function of MMP‐9 sheddase restore T cell‐mediated cancer killing." (PMID 34486239, 2021). "Because SNAI1, FN1, and MMP9 play a key role in inducing EMT-associated cancer plasticity, chemoresistance, and metastasis, we aimed to define the pivotal role of AURKA in mediating TGF-β-induced expression of SNAI1, FN1, and MMP9 genes." (PMID 33674749, 2021). "Overexpressed levels of matrix metallopeptidase-9 (MMP-9) are associated with cancer invasion, metastasis, and inflammation In vivo." (PMID 33917027, 2021). "Several studies have indeed shown that galectin-7 is associated with aggressive behavior of cancer cells and induces expression of MMP-9, a member of the matrix metalloproteinases (MMP) family known to confer invasive behavior to cancer cells." (PMID 34198494, 2021). "HuR interacts with and/or regulates many transcripts involved in the development of cancer cells, such as cyclins, matrix metalloproteinase-9 (MMP-9), metastasis-associated protein 1 (MTA1), anti-apoptotic protein pro-thymosin α (ProTalpha) and HIF-1α." (PMID 34638733, 2021). "Numerous studies have implicated MMP2 and MMP9 as active contributors of malignant progression because they enhance cancer cell migration and invasion." (PMID 34142438, 2021). "OPN binding to integrin activates nuclear factor kappa-light-chain-enhancer of activated B cells (NF-κB)-mediated signaling, which modulates the MAPK pathway and upregulates MMP-9, causing increased cancer cell migration and invasion." (PMID 34067095, 2021). "Many lines of evidence suggest that BRAF MT is associated with the upregulation of MMP9 expression in several cancers." (PMID 34069882, 2021). "It was revealed that the potential cancer risk predictors are age, 20S proteasome level in exosomes, MMP9 + and MMP9+/MMP2+/EMMPRIN+ subpopulations of CD9-positive exosomes." (PMID 33773551, 2021).